RFWD3 (ring finger and WD repeat domain 3)
Description:
E3 ubiquitin-protein ligase required for the repair of DNA interstrand cross-links (ICL) in response to DNA damage. Plays a key role in RPA-mediated DNA damage signaling and repair. Acts by mediating ubiquitination of the RPA complex (RPA1, RPA2 and RPA3 subunits) and RAD51 at stalled replication forks, leading to remove them from DNA damage sites and promote homologous recombination. Required to translesion DNA synthesis across DNA-protein cross-link adducts by catalyzing ubiquitination of proteins on single-stranded DNA (ssDNA).
Synonyms: RNF201; FLJ10520; FANCW
Tractability: PROTAC: ubiquitination databases record sites on it.
Gene: Protein-coding gene on chromosome 16 (74,621,393 to 74,666,912, reverse strand). Ensembl gene ENSG00000168411.
Subcellular location: Nucleus; Nucleus, PML body; Cytoplasm
Subcellular location (Human Protein Atlas): Nucleoplasm; Cytosol
Gene Ontology:
Molecular function: MDM2/MDM4 family protein binding; protein binding; ubiquitin protein ligase activity; ubiquitin-protein transferase activity
Biological process: DNA damage response; double-strand break repair via homologous recombination; interstrand cross-link repair; mitotic G1 DNA damage checkpoint signaling; protein ubiquitination; regulation of DNA damage checkpoint; replication fork processing; response to ionizing radiation
Cellular component: cytoplasm; cytosol; nucleoplasm; nucleus; site of DNA damage; site of double-strand break; PML body
Genetic constraint (gnomAD): Loss-of-function variants: 60 observed, 79.88 expected, observed/expected ratio (o/e) 0.75, 90% interval 0.61 to 0.93. The upper end of that interval is the gene's LOEUF score, 0.93, which puts it in group 3 of 6, group 1 being the genes least tolerant of losing a copy. Missense variants: 1,004 observed, 921.51 expected, observed/expected ratio (o/e) 1.09, 90% interval 1.03 to 1.15. Synonymous variants: 402 observed, 345.64 expected, observed/expected ratio (o/e) 1.16, 90% interval 1.07 to 1.26.
Homologues: Orthologues: chimpanzee RFWD3 (99% identical), macaque RFWD3 (95% identical), pig RFWD3 (78% identical), dog RFWD3 (77% identical), rabbit RFWD3 (76% identical), rat Rfwd3 (69% identical), guinea pig RFWD3 (69% identical), mouse Rfwd3 (68% identical), tropical clawed frog rfwd3 (52% identical), zebrafish rfwd3 (41% identical), Drosophila melanogaster mus302 (21% identical), Drosophila melanogaster CG13481 (6% identical), and 4 more.
Diseases named in the same sentence as RFWD3 in open-access papers:
RFWD3 is named in the same sentence as 27 diseases in open-access papers, as found by Europe PMC text mining. Sharing a sentence is not in itself a finding about the gene and the disease. The quoted sentences say what the papers report.
Fanconi anemia (13 papers, 2018 to 2025). Fanconi anemia (FA) is a hereditary DNA repair disorder characterized by progressive pancytopenia with bone marrow failure, variable congenital malformations and predisposition to develop hematological or solid tumors. "RFWD3, a recently described Fanconi anemia (FA) ubiquitin ligase, associates with RPA and promotes its ubiquitylation, facilitating late steps of homologous recombination (HR)." (PMID 38502677, 2024). "Recently, a patient was reported with a typical Fanconi anemia phenotype with heterozygous mutations in RFWD3." (PMID 35905994, 2022). "Because a point mutation in RFWD3 at the residue crucial for its function in ICL repair causes Fanconi anemia, it is possible that mutations in RFWD3 at sites associated with DNA damage tolerance cause photosensitive disorders." (PMID 35905994, 2022). "Mutations in RFWD3 cause Fanconi anemia (MIM: 617784), a disease linked to telomere shortening and/or abnormalities." (PMID 32109421, 2020). "RFWD3 is a Fanconi anemia protein; a mutation in this protein in Fanconi anemia patients interferes with ubiquitination of RPA and RAD5124,31–33." (PMID 31582797, 2019). "Finally, patients biallelic for inactivating mutations in RFWD3 display Fanconi Anemia-like symptoms, so this gene has also been named FANCW." (PMID 31900333, 2020). "Furthermore, a Fanconi Anemia phenotypes causing patient mutation in RFWD3 leads to deregulation of RPA reactions at the replication fork." (PMID 29334356, 2018). "Familial missense mutations in RFWD3 abolish RPA ubiquitination and cause Fanconi anemia (FA), which is characterized by defects in interstrand crosslink repair." (PMID 41372167, 2025). "RFWD3 is also closely associated with the DNA damage response (DDR) and Fanconi anemia (FA) signaling pathways, which coordinate various DNA repair mechanisms." (PMID 40002911, 2025). "Mutations in RFWD3, which was previously reported as the FANCW gene, result in Fanconi anemia." (PMID 35905994, 2022). "Mutations in RFWD3 lead to defects in ICL repair by disrupting RPA-RFWD3 binding at ICL—induced stalled replication forks and have been associated with Fanconi anaemia (FA), a rare genetic disorder characterised by genomic instability and predisposition to cancer." (PMID 34066546, 2021).
gastric cancer (4 papers, 2020 to 2024). A primary or metastatic malignant neoplasm involving the stomach. "A link between reduced RFWD3 expression and impaired cell proliferation has been previously shown in lung, colorectal and gastric cancers." (PMID 38711848, 2024). "RFWD3 (FANCW) knockdown increases sensitivity to DNA damaging agents, and increased expression following DNA damage in gastric cancer has been shown, although little other information exists linking it to cancer." (PMID 36046263, 2020). "The published literature mentioned that the high expression of RFWD3 was involved in the occurrence and development of gastric carcinoma, and may be an important poor prognostic factor of gastric carcinoma." (PMID 34712656, 2021).
multiple myeloma (3 papers, 2019 to 2025). "RFWD3 (ring finger and WD repeat domain 3), a myeloma risk gene at 16q23.1, is also involved in the UPS: it encodes an E3 ubiquitin ligase that participates in DDR in association with the replication protein A complex." (PMID 31139207, 2019). "The multiple myeloma susceptibility locus, rs7193541, was located in the exon of RFWD3 in 16q23.1." (PMID 32010612, 2019).
colorectal cancer (2 papers, 2021 to 2024). A primary or metastatic malignant neoplasm that affects the colon or rectum. "In gastric and colorectal cancer, RFWD3 was also associated with a cell migratory phenotype." (PMID 38711848, 2024). "Expression patterns of RFWD3 in colorectal cancer tissues and para-carcinoma tissues revealed in immunohistochemistry analysis." (PMID 34712656, 2021). "Relationship between RFWD3 expression and tumor characteristics in patients with colorectal cancer." (PMID 34712656, 2021).
lung carcinoma (2 papers, 2019 to 2025). "Exposure to cigarette smoke and haze (PM2.5) upregulate RFWD3 via transcription factor AhR, while inhibition of RFWD3 enhances the therapeutic efficacy of PD‐L1 blockade, providing a potential approach to tackle smohaze‐induced lung cancer." (PMID 41117130, 2025). "Thus, RFWD3 is able to reprogram TME to promote carcinogenesis, and inhibition of RFWD3 can effectively repress the progression of lung cancer in mice." (PMID 41117130, 2025). "The E3 ubiquitin ligase RFWD3 binds the exonuclease TREX1 and protects it from TRIM24‐mediated ubiquitination and degradation, leading to the eradication of intracellular dsDNA, inhibition of the cGAS‐STING pathway, and immunosuppressive microenvironment of lung cancer." (PMID 41117130, 2025).
non-small cell lung carcinoma (2 papers, 2021). A group of at least three distinct histological types of lung cancer, including non-small cell squamous cell carcinoma, adenocarcinoma, and large cell carcinoma.
Azoospermia (1 paper, 2022). Absence of any measurable level of sperm,whereby spermatozoa cannot be observed even after centrifugation of the semen pellet. "In non-obstructive azoospermia, the gene ATPase phospholipid transporter 9A (ATP9A) was upregulated, whereas the ring finger and WD repeat domain 3 (RFWD3) and phosphatidylinositol glycan anchor biosynthesis class K (PIGK) were downregulated." (PMID 36293429, 2022).
breast carcinoma (1 paper, 2025). "Meanwhile, we found that RFWD3 also regulates the sensitivity of other malignancies to DDP treatment, such as melanoma and breast cancer." (PMID 40019400, 2025).
colorectal adenocarcinoma (1 paper, 2021). The most common type of colorectal carcinoma. "Except for detecting RFWD3 level in CRC tumor tissues, the mRNA and protein expression of RFWD3 in human colorectal adenocarcinoma epithelial cell DLD-1 and a panel of CRC cell lines was evaluated by qRT-PCR and western blot analysis." (PMID 34712656, 2021).
endometrial cancer (1 paper, 2025). Primary or metastatic malignant neoplasm involving the endometrium (mucous membrane that lines the endometrial cavity). "To validate the differential expression of ZNF626, SLK, and RFWD3 proteins in endometrial cancer (EC), we compared their expression levels in EC tissues with those in normal endometrial tissues." (PMID 40002911, 2025). "Therefore, ZNF626, SLK, and RFWD3 may represent potential therapeutic targets for endometrial cancer." (PMID 40002911, 2025). "Although the roles of ZNF626, SLK, and RFWD3 in endometrial cancer have not been extensively discussed, their biological functions in relation to other tumors are well documented and can provide insights for our study." (PMID 40002911, 2025).
Lewis Lung Carcinoma (1 paper, 2025). "First, C57BL/6 mice were subcutaneously transplanted with control or RFWD3 knockdown murine Lewis Lung Carcinoma (LLC) cells that are insensitive to immune checkpoint inhibitors (ICI), and we found that knockdown of RFWD3 significantly inhibited tumor growth and reduced tumor weight." (PMID 41117130, 2025).
lung squamous cell carcinoma (1 paper, 2025). "Silencing of RFWD3 in lung squamous cell carcinoma (LUSC) H2170 cells also led to upregulation of p‐STING, p‐TBK1, p‐IRF3, and p‐STAT1." (PMID 41117130, 2025).
meningioma (1 paper, 2023). A generally slow growing tumor attached to the dura mater. "Six antigens were exclusively found in the immunopeptidome of WHO grade I meningiomas (CAPN14, KIR2DS4, TMM44, ECD, CD86, and RFWD3), whereas WHO grade I and III meningiomas showed only one antigen in common (KLC2)." (PMID 37368072, 2023).
osteosarcoma (1 paper, 2025). A usually aggressive malignant bone-forming mesenchymal neoplasm, predominantly affecting adolescents and young adults. "The data revealed that the loss of RFWD3 markedly enhanced the sensitivity of osteosarcoma to DDP treatment." (PMID 40019400, 2025). "Overall, our study elucidates the mechanistic underpinnings of RFWD3 regulation in DDP resistance and suggests that targeting RFWD3 and its associated metabolic pathways represents a promising strategy for osteosarcoma treatment." (PMID 40019400, 2025). "Given the critical role of PHGDH as a metabolic enzyme, we proceeded to investigate the influence of RFWD3 on the metabolic pathways in osteosarcoma cells." (PMID 40019400, 2025). "Here, RFWD3 is identified as a key regulator of DDP sensitivity in osteosarcoma using a genome‐wide CRISPR screen." (PMID 40019400, 2025). "In conclusion, a specific role of RFWD3 in regulating nucleotide metabolism is revealed and comprised of targetable candidates for overcoming chemoresistance in osteosarcoma." (PMID 40019400, 2025). "It is demonstrated that RFWD3 is overexpressed in post‐chemotherapy osteosarcoma tissues compared to pre‐chemotherapy tissues." (PMID 40019400, 2025). "Further survival analysis utilizing the R2 online database revealed that elevated RFWD3 expression correlates with poor prognosis in osteosarcoma patients." (PMID 40019400, 2025). "To address this, we first examined the expression of RFWD3 in osteosarcoma cells and three other cell types from the tumor microenvironment (hMBSC, hFOB1.19, and HSF)." (PMID 40019400, 2025). "We found that RFWD3 expression was significantly higher in osteosarcoma cells compared to the other three cell types." (PMID 40019400, 2025). "In summary, this study identifies the RFWD3/PHGDH axis as a pivotal regulator of DDP resistance in osteosarcoma." (PMID 40019400, 2025). "Collectively, these findings indicate that RFWD3 is a pivotal regulator of DDP sensitivity in osteosarcoma." (PMID 40019400, 2025). "To further validate the impact of RFWD3 on DDP resistance in osteosarcoma, we generated RFWD3 knockout cells utilizing the CRISPR/Cas9 system." (PMID 40019400, 2025). "Further investigation revealed that, in addition to regulating DNA repair proteins, RFWD3 reprograms nucleotide metabolism in osteosarcoma cells to induce cisplatin resistance." (PMID 40019400, 2025). "Subsequent analysis of metabolites associated with nucleotide metabolism indicated a marked downregulation in RFWD3 knockout osteosarcoma cells compared to the control group." (PMID 40019400, 2025). "RFWD3 is identified as a key regulator of cisplatin (DDP) sensitivity in osteosarcoma using a genome‐wide CRISPR screen." (PMID 40019400, 2025). "Additionally, we assessed RFWD3 expression levels in osteosarcoma tissues pre‐ and post‐chemotherapy." (PMID 40019400, 2025). "However, we found that a high dose of NCT‐503 further inhibited the growth of RFWD3 knockout osteosarcoma cells under DDP treatment." (PMID 40019400, 2025). "The results showed that RFWD3 knockout significantly reduced chemoresistance in osteosarcoma." (PMID 40019400, 2025). "Next, the knockdown of PHGDH or inhibition of PHGDH activity could eliminate the effect of RFWD3 knockdown on NAD+ and serine level, indicating that RFWD3 modulated osteosarcoma cell metabolism via PHGDH." (PMID 40019400, 2025). "Knocking out RFWD3 increased the sensitivity of osteosarcoma cells to DDP treatment." (PMID 40019400, 2025). "Additionally, DDP treatment significantly elevated the ubiquitination levels of PHGDH, indicating that PHGDH ubiquitination by RFWD3 may play a crucial role in osteosarcoma cells’ response to DDP treatment." (PMID 40019400, 2025). "Furthermore, we wondered whether RFWD3 specifically regulates the sensitivity to DDP only in osteosarcoma cells." (PMID 40019400, 2025). "In summary, lomitapide disrupts the interaction between RFWD3 and PHGDH, thereby enhancing cisplatin sensitivity in osteosarcoma." (PMID 40019400, 2025).
osteosarcoma (continued). "Additionally, Lomitapide, a specific RFWD3‐PHGDH interaction inhibitor, synergistically enhanced the anti‐osteosarcoma effect of DDP, offering potential therapeutic insights." (PMID 40019400, 2025). "The results showed that the effect of RFWD3 knockout on DDP sensitivity could be partially mitigated by a low dose of the PHGDH inhibitor NCT‐503, indicating that PHGDH partially mediated the RFWD3‐induced DDP resistance in osteosarcoma." (PMID 40019400, 2025).
rectum cancer (1 paper, 2021). "The SNHG1 ceRNA network is common for all CRC sites, but only interacts with RFWD3 and E2F8 in the rectum, indicating a potential role for this network in rectum cancer." (PMID 34178670, 2021).